CRP (C-reactive protein)
Diseases named in the same sentence as CRP in open-access papers (continued):
Sharing a sentence is not in itself a finding about the gene and the disease.
Obesity (continued). "In addition, common variants in BHLHE40-AS1 associate with gamma glutamyl transferase, a biomarker positively correlated with C-reactive protein and increased oxidative stress, which is supported by our PheWAS of Obesity Class III trait in UKBB." (PMID 40939575, 2025). "Therefore, the aim of this secondary analysis was to compare the effects of TRE versus CR on key inflammatory markers (TNF-alpha, IL-6, and CRP) in adults with obesity over 12 months." (PMID 40218888, 2025). "This pathogenesis was connected to higher CRP, which may be observed to be higher in rapid growth children with obesity." (PMID 40822418, 2025). "A middle-aged person with obesity/T2D; hs-CRP 6.2 mg/L, NLR 3.4, triglycerides high." (PMID 41440484, 2025). "In recent decades, the role of serum biomarkers in relation to obesity has been thoroughly studied, and it has been concluded that C-reactive protein, ferritin, white blood cell count, and red cell distribution width are direct inflammatory biomarkers of obesity-related inflammation in children." (PMID 40282897, 2025). "The reduction of obesity indirectly improved CRP levels and reduced inflammation in patients." (PMID 40642165, 2025). "In individuals with obesity and related pathologies, resveratrol supplementation at doses of 500 mg/day or higher for over 12 weeks has been shown to reduce inflammatory markers like C-reactive protein (CRP) and TNF-α, alongside a decrease in BMI." (PMID 40943464, 2025). "In addition, both CRP and IL-6 are affected by metabolic conditions (e.g., obesity and insulin resistance), which can independently affect NO metabolism." (PMID 39981124, 2025). "Therefore, the reduction in ferritin and CRP levels observed in this study reflects an improvement in the inflammatory parameters of patients with severe obesity." (PMID 39746069, 2025). "White and red blood cell count, thrombocyte, sodium, glucose, insulin, HbA1c, uric acid, triglyceride, LDL-cholesterol, ASAT/GOT, ALAT/GPT, GGT, alkaline phosphatase, ferritin and CRP values were significantly higher in patients with obesity compared to controls with a normal BMI." (PMID 40463745, 2025). "Post hoc analysis showed that the normal group had significantly lower CRP/Alb ratios than all obesity classes (p < 0.001), while individuals with Class III obesity exhibited higher CRP/Alb levels compared to the overweight (p = 0.0002) and Class I obesity (p = 0.0285) groups." (PMID 41302334, 2025). "Considering that metabolic syndrome is regarded as a clinical manifestation of insulin resistance, the increase in CRP levels may indirectly reflect progressive metabolic deterioration in individuals with higher degrees of obesity." (PMID 40951687, 2025). "In more recent research, the Korean Genome and Epidemiology Study (KoGES) study (2019) involving nearly 23,000 individuals confirmed a positive association between higher CRP levels and incident T2DM, particularly in older populations and in the presence of obesity and hypertension." (PMID 40725102, 2025). "Our results show that, similar to nonpregnant individuals, overweight and obesity in pregnancy are associated with an unfavorable inflammatory phenotype compared to normal weight, mirrored by higher CRP levels in the first trimester." (PMID 40329709, 2025). "Notably, these associations were more pronounced in women, emphasizing the gender-specific influence of obesity on CRP levels, and we found a correlation of 0.41 in the present all-female sample." (PMID 40001459, 2025). "In nonpregnant individuals, C‐reactive protein (CRP) has consistently been associated with overweight and obesity in various epidemiological studies." (PMID 40329709, 2025). "The reductions in CRP and TNF-α are clinically significant, given their established associations with cardiometabolic disorders, including cardiovascular disease, type 2 diabetes, and obesity." (PMID 41301508, 2025).
Obesity (continued). "Furthermore, our recent findings showed elevated peripheral inflammatory markers including C-Reactive Protein (CRP) and interleukin (IL)-6 in individuals with overweight/obesity and depression compared to individuals with these conditions alone." (PMID 40585350, 2025). "Visceral adipose tissue is an active endocrine organ that secretes proinflammatory cytokines such as tumor necrosis factor-alpha (TNF-α), interleukin-6 (IL-6), and C-reactive protein (CRP), which contribute to systemic low-grade inflammation, a hallmark of obesity-related metabolic dysfunction." (PMID 40805992, 2025). "The results of our study suggest that PBM may offer potential benefits for treating obesity, showing some improvements in key indicators such as BMI, weight, waist circumference, CRP, TC, and HOMA-IR compared to exercise, dietary changes, and sham PBM." (PMID 40217252, 2025). "In severe obesity, Seshadri reported an additional ~−2 mg/L with low-carbohydrate intake in the subgroup with baseline CRP > 3 mg/L, independent of weight loss." (PMID 41305609, 2025). "Furthermore, there is a need for prospective studies to determine if salivary CRP can predict future inflammation‐related complications in children and adolescents with obesity before it can be used to monitor the effectiveness of interventions." (PMID 40547317, 2025). "Another review conducted in adults with overweight or obesity, but that performed a meta-analysis, showed similar effects of DF intake on circulating CRP concentrations, showing a significant reduction in this inflammatory marker compared to the C group (–0.37 mg/L; (95% CI: –0.74, 0 mg/L)." (PMID 40949172, 2025). "In this study, we instead used a percent change in CRP as this may partially control for confounding factors influencing baseline CRP levels, such as obesity or the individual response to the surgical insult." (PMID 40363964, 2025). "Current smoking (OR = 1.76, 95% CI [1.26–2.45], p = 0.001), elevated CRP (1–3 mg/L: OR = 1.40, 95% CI [1.04–1.87], p = 0.026; ≥3 mg/L: OR = 1.63, 95% CI [1.00–2.66], p = 0.033), and obesity (OR = 8.29, 95% CI [6.12–11.21], p < 0.001) significantly increased the likelihood of CMRC." (PMID 41301855, 2025). "Furthermore, compared to the controls, the dental caries group demonstrated a higher tendency to suffer from obesity, a lower education level, and lower family income, as well as higher values of CRP, leukocytes, neutrophils, and lymphocytes." (PMID 41384444, 2025). "Inflammation in obesity can increase the activity of lactate dehydrogenase, C-reactive protein (CRP), and plasminogen activator inhibitor-1 (PAI-1), thereby enhancing lactate oxidation, LDL expression in neurons, and mitochondrial ROS synthesis, leading to neurodegeneration and memory impairment." (PMID 41465437, 2025). "The study hasalso indicated that obesity is associated with changes in glycoproteinacetylation but not with CRP and NLR." (PMID 40926826, 2025). "Children with overweight or obesity measured by BMI were more likely to have lower vitamin D level, increased leukocyte counts and C-reactive protein levels, increased blood triglycerides and decreased high density lipoprotein values, compared to the normal weight group." (PMID 41257907, 2025). "The previous study also demonstrated elevated CRP in adults with obesity." (PMID 39940324, 2025). "The current findings support that high CRP in PCOS patients is more closely related to obesity." (PMID 40572700, 2025). "The presence of CRP in obesity signifies chronic inflammation." (PMID 40822418, 2025). "CRP is known to be elevated in obesity and metabolic diseases." (PMID 40805975, 2025). "Hospitalization length may be prolonged by inflammation markers (WBC and CRP) and comorbidities such as AF, obesity, or the need for enoxaparin in patients with elevated thrombosis risk." (PMID 40806921, 2025).
Obesity (continued). "CRP, as a widely studied traditional inflammatory biomarker, is known to be an acute-phase protein synthesized by liver cells in response to inflammation triggered by various factors, such as infection or obesity." (PMID 40041151, 2025). "In our study, patients with obesity had higher levels of CRP at follow-up, which could indicate inadequate response to treatment, or be associated with the obesity as a low-grade inflammatory state." (PMID 41141372, 2025). "Women suffering from obesity were found to have elevated levels of both CRP and PGE2, and the concentration of pro-inflammatory eicosanoids was positively correlated not only with the anthropometric parameters of the patients, but also with the level of CRP in the blood." (PMID 41294849, 2025). "Recent research has highlighted the complex relationship between obesity and chronic inflammation, with studies such as demonstrating that elevated CRP levels are not only indicative of acute infections but also reflect chronic inflammatory states associated with obesity." (PMID 40041151, 2025). "Monitoring salivary CRP levels could aid in targeting interventions to prevent obesity‐related complications early in life." (PMID 40547317, 2025). "In multivariable analyses, higher CRP (β 0.21, p = 0.04) at baseline was associated with higher LV mass index at baseline, independent of sex, age and presence of obesity." (PMID 41141372, 2025). "In the first trimester, CRP was 1.7‐fold higher in overweight women (mean 5.9 mg/L; 95% CI 5.0 to 6.7; p < 0.0001) and 2.7‐fold higher in those with obesity (mean 9.3 mg/L; 95% CI 7.6 to 11.0; p < 0.001) compared to normal‐weight women (mean 3.4 mg/L; 95% CI 3.1 to 3.7)." (PMID 40329709, 2025). "Additionally, like we discussed, CRP itself is confounded by obesity, metabolic syndrome, all of which are highly prevalent in HS, which complicates the interpretation of treatment-related changes." (PMID 41458786, 2025). "Chronic pain was also positively genetically correlated with levels of the immune biomarker C-reactive protein (CRP) and with insomnia and anthropometric or metabolic traits, including body mass index (BMI), obesity, Type 2 diabetes, and hip and waist circumference." (PMID 40297705, 2025). "Key predictive proteins such as C9, TTR, CRP, and S100A9 are not only differentially abundant in obesity but also implicated in the pathogenesis of endothelial dysfunction, systemic inflammation, and insulin resistance, further validating their mechanistic relevance." (PMID 40981199, 2025). "Although both share a chronic inflammatory state, the underlying mechanisms are different: in SLE, the inflammation is of autoimmune origin, whereas in MI it is related to obesity and insulin resistance, which may affect CRP expression." (PMID 39468772, 2025). "First, obesity is associated with a state of chronic low-grade systemic inflammation, characterized by elevated levels of pro-inflammatory cytokines, including tumor necrosis factor-alpha (TNF-α), interleukin-6 (IL-6), C-reactive protein (CRP), and resistin." (PMID 40426647, 2025). "Background/Objectives: Obesity is associated with chronic systemic inflammation and elevated levels of inflammatory cytokines such as tumor necrosis factor alpha (TNF-alpha), interleukin-6 (IL-6), and C-reactive protein (CRP)." (PMID 40218888, 2025). "In the NHANES, the association between HEI-2015 and all-cause mortality was absent among individuals with obesity and severe inflammation (CRP > 3 mg/L), but remained significant in those with moderate (CRP 1–3 mg/L) or low inflammatory burden (CRP < 1 mg/L)." (PMID 41051618, 2025). "This suggests that the increase in CRP occurs due to the inflammatory state of obesity, and may be an important indicator in the diagnosis of cardiovascular and metabolic complications in adolescent." (PMID 40717997, 2025).
Obesity (continued). "Complement proteins are increased in polycystic ovary syndrome (PCOS), as are markers of inflammation, such as the C-reactive protein (CRP); however, both may be increased in obesity." (PMID 40243681, 2025). "Changes in obesity-related measures have also been correlated with changes in IL-6 and CRP." (PMID 40895542, 2025). "A meta-analysis investigating the association between PCOS and CRP demonstrated that CRP levels are elevated in PCOS independent of obesity, supporting the role of chronic low-grade inflammation in PCOS pathogenesis." (PMID 41464800, 2025). "The fact that we could not detect any sex differences in our sample is most likely due to the large age range (18 to 63 years) and BMI variability (17.5 to 45.2), since both age and obesity influence CRP-levels in a sex-specific manner." (PMID 40980040, 2025). "This study assessed the anti-inflammatory potential of a Mediterranean-style ketogenic diet and its effects after 7 months of adherence on systemic inflammation markers (CRP and IL-6) in women with lipedema (n = 24) and a control group with overweight/obesity (n = 24)." (PMID 41010539, 2025). "Both groups with obesity had higher CRP levels than the control group." (PMID 40005412, 2025). "Therefore, potential effects of CCJ12 on various obesity-related risk factors (bodyweight, cholesterol, HDL, LDL, and triglycerides, leptin, adiponectin, sE-selectin, CRP, MCP-1 and TNF-alpha) were studied in rats fed a high fat diet." (PMID 40770283, 2025). "Obesity and the resulting adipose tissue inflammation thus eventually results in a generalized, low-grade, systemic inflammation with the elevation of pro-inflammatory cytokines (C-reactive protein [CRP], TNF-α)." (PMID 41296415, 2025). "Obesity often leads to a chronic low-grade inflammatory state, marked by elevated levels of pro-inflammatory cytokines such as interleukin-6 (IL-6) and high-sensitivity C-reactive protein (Hs-CRP)." (PMID 40641901, 2025). "Obesity is also linked to subclinical chronic inflammation, characterised by the release of pro-inflammatory proteins into the circulation, including IL-6, TNF α, interleukin 8 (IL-8), and high-sensitivity C-reactive protein (C-RP hs)." (PMID 40310144, 2025). "Additionally, obesity, socioeconomic deprivation, elevated C-reactive protein, triglyceride, vitamin D, HbA1c, cystatin C, urate, and alanine aminotransferase, and decreased HDL cholesterol and IGF-1, as well as CKD and COPD, were associated with LC." (PMID 40738888, 2025). "It was speculated that higher CRP levels in people with obesity may be related to higher DBP serum levels, but our findings did not support this idea." (PMID 40041287, 2025). "The absence of inflammatory biomarkers (e.g., CRP, IL-6) limits our ability to investigate the underlying mechanisms linking obesity to RA." (PMID 40362866, 2025). "Obesity was also linked to elevated levels of TNF-α and PAI-1, whereas insulin resistance, dyslipidemia, and metabolic syndrome were linked to elevated levels of CRP." (PMID 40642705, 2025). "Secondly, the results showed a significant correlation between obesity and NLRand CRP levels." (PMID 40926826, 2025). "From a biological perspective, obesity-related chronic inflammation may accelerate atherosclerosis by promoting systemic inflammatory responses (e.g., CRP, IL-6), increasing plaque vulnerability and thereby compounding stroke risk." (PMID 41041669, 2025). "Then, potential effects of CCJ12 on adipokines (leptin and adiponectin), cardiovascular (sE-selectin and C-reactive protein), and inflammatory (MCP-1 and TNF-alpha) factors were studied, because these factors are also associated with obesity as well as other diseases." (PMID 40770283, 2025). "Women generally exhibit stronger innate and adaptive immuneresponses, which could lead to a heightened inflammatory response to obesity andcontribute to the stronger link between obesity and CRP." (PMID 40926826, 2025).
Obesity (continued). "A couple of trials in adults with obesity have found no change in circulating CRP due to the minimal amount of weight loss attained (3–5% from baseline)." (PMID 40218888, 2025). "Consistent with previous studies, elevated YKL-40 levels were associated with obesity, alcohol overconsumption, smoking, and lower kidney function, as well as higher triglycerides and CRP, but not with LDL cholesterol." (PMID 40188292, 2025). "The present study aims to investigate the association of GHSR-1a immunopositive (+) cells from atherosclerotic plaque and PVAT with inflammatory markers (tissue concentrations of CRP, Il-6, leptin, and adiponectin) by studying the arteries harvested from patients with obesity and PAD." (PMID 40137085, 2025). "The association was stronger in women, older adults, those with obesity, lower systemic inflammation (hs-CRP ≤ 3 mg/L), and non-smokers, non-drinkers, and non-snorers." (PMID 41023603, 2025). "Furthermore, serum Sfrp5 concentrations in subjects with coronary artery disease (CAD) and adults with obesity were inversely related to hs-CRP concentrations." (PMID 39339733, 2024). "Other DAMPs involved in TLR-4/9 and canonical NLRP3 inflammasome activation in obesity include elevated palmitate and other saturated fatty acids, glucose, uric acid, C-reactive protein (CRP), ceramide, islet amyloid polypeptide, HMGB1, mitochondrial DNA, and cholesterol crystals/oxLDL." (PMID 39063184, 2024). "They found that obesity, IGT, and T2DM were associated with increased IL-6 and CRP levels." (PMID 39408723, 2024). "Therefore, our findings concerning CRP and leptin levels reinforce the idea that obesity-related inflammation begins early in childhood." (PMID 39768291, 2024). "Additionally, VAT can also induce obesity-related subclinical inflammatory changes, such as increased production of interleukin-6, tumour necrosis factor-α, and C-reactive protein, which can precede the pathogenesis of CKD." (PMID 39698033, 2024). "Obesity often correlates with heightened levels of systemic pro-inflammatory markers like C-reactive protein, TNF-α, TGF-β, leptin, and IL-6, and we have shown that reducing TNF-α and TGF-β1 levels improved AHR and fibrosis in the same HFD-induced obesity model." (PMID 38762465, 2024). "The investigators provided evidence that CRP is not merely a marker of inflammation, but instead has a causal role in the development of obesity." (PMID 38978699, 2024). "In psychiatric patients, the prognostic role of CRP may be particularly important due to the frequent presence of comorbidities such as metabolic syndrome, cardiovascular disease, and obesity, all of which independently contribute to higher CRP levels." (PMID 39408010, 2024). "Moreover, obesity leads to heightened leptin levels and inflammatory markers such as C-reactive protein (CRP), further exacerbating vascular and myocardial injuries." (PMID 38397015, 2024). "CRP may be involved in the biochemical process that results from obesity to short telomere length via low-grade inflammation, accelerated cell turnover in the bone marrow and subtle alterations in leukocyte distribution." (PMID 39057051, 2024). "However, the consistent increase of CRP and fibrinogen with BMI suggests that obesity contributes indirectly to CVD progression by promoting systemic inflammation." (PMID 39595090, 2024). "A population-based study also linked elevated CRP levels to higher depressive symptoms in men, independent of other risk factors, whereas obesity confounded the relationship in women." (PMID 39769178, 2024). "In addition, CRP levels differences across individuals were found to be influenced by lifestyle factors, for example obesity and ethnicity." (PMID 39610697, 2024). "Additionally, the review observed a stronger correlation between CRP levels and obesity among Europeans and Americans compared to an Asian population." (PMID 39769504, 2024). "It is reported that each degree of obesity was directly correlated with CRP." (PMID 38685027, 2024).